BRAF (B-Raf proto-oncogene, serine/threonine kinase)
Diseases named in the same sentence as BRAF in open-access papers (continued):
Sharing a sentence is not in itself a finding about the gene and the disease.
melanoma (continued). "Melanomas with PI3K–Akt-activating mutations showed that the reactivation of the MAPK pathway is the main mechanism of resistance to BRAF inhibitors." (PMID 35335966, 2022). "To demonstrate the ability of this BRAF score to encapsulate pathway activity, we showed that BRAF score can identify BRAF V600E mutation status and additional gene aberrations within TCGA melanoma tumor samples." (PMID 35044091, 2022). "For melanoma, BRAF and NRAS mutations are considered to be important disease-driving oncogenes and were included in the mutation analysis performed in this study." (PMID 36531960, 2022). "Trametinib is a MEK inhibitor, which significantly inhibits the activation of the MAPK pathway in the malignancies such as melanomas with BRAF fusion mutation." (PMID 36430869, 2022). "Together, these data suggest that NAMPT over-expression positively influences the capacity of melanoma cells to grow even independently from the mutations on the key oncogene BRAF." (PMID 35272691, 2022). "For example, targeted therapies have established intracranial activity in patients with Her2-positive breast cancer BM, ALK-rearranged or EGFR-mutated NSCLC BM and for BRAF V600E mutated melanoma BM." (PMID 36605448, 2022). "Despite showing potent efficacy in BRAF-mutated melanoma, MEK inhibitors appeared to be tolerated by colorectal cancer cells due to their intrinsic compensatory signaling." (PMID 34718347, 2022). "While BRAF-V600E is the most common pathogenic mutation seen in cutaneous sun-exposed melanomas, mucosal and anogenital melanomas usually lack BRAF mutations and instead harbor KIT alterations." (PMID 36407184, 2022). "This was demonstrated by the development of highly selective BRAF inhibitors (vemurafenib and dabrafenib) for melanoma patients after the identification of the target mutation." (PMID 36292642, 2022). "BRAF mutations are present in around 50% of cutaneous malignant melanomas and are related to a poor outcome in advanced-stage melanoma patients." (PMID 35326682, 2022). "The anti-tumor effect of DPG was evaluated using a melanoma cell line (SK-MEL-28) carrying BRAF mutation." (PMID 35806253, 2022). "BRAF fusion mutation is detected in low rates in melanoma, gliomas, and anaplastic thyroid cancer, and confers on cancer cells acquired drug resistance." (PMID 36430869, 2022). "We treated BRAF-mutated human melanoma cell lines A2058, A375, and C8161, respectively, with bepridil, CB-DMB, KB-R7943, SN-6, or YM-244769 for 48 h." (PMID 35055084, 2022). "On the other hand, BRAF mutated patients had higher rates of necrosis in primary site and lymphovascular invasion than BRAF wild-type (WT) melanoma patients." (PMID 35160279, 2022). "Although depletion of USP9X reduces tumor growth in melanoma cells carrying BRAF or NRAS mutations, its combination with MAPK pathway inhibitors (vemurafenib or MEKi) has been shown to enhance the therapeutic response." (PMID 35884430, 2022). "The BRAF V600E mutation is found across cancer types including >97% of hairy cell leukemias, 40–67% of melanomas, 36–69% of papillary thyroid tumors, 15–20% of low-grade pediatric tumors, and 5–17% of colorectal cancers." (PMID 35565240, 2022). "In primary cancer we found two enriched variants of BRAF, in melanoma and thyroid cancer, these are both variants that can be targeted by treatment and therefore likely are selected against in development of metastatic cancer." (PMID 36497297, 2022). "BRAF-mutated melanoma patients can receive targeted therapies or immunotherapies, while BRAF wild-type melanoma patients receive immunotherapies." (PMID 36077308, 2022). "More than half of melanomas present the activating BRAF mutations, along which V600E mutant represents 70%–90%." (PMID 36034784, 2022). "BRAF mutation seems to be more frequent in the Caucasian population, with a higher incidence of V600K mutated melanomas." (PMID 35160279, 2022).
melanoma (continued). "For instance, v-raf murine sarcoma viral oncogene homologue B1 (BRAF), one of the most frequently mutated protein kinase genes in human cancers, mutations are seen in melanoma, papillary thyroid carcinoma, and CRC." (PMID 35152308, 2022). "It has been shown that HGF secreted by fibroblasts causes the primary insensitivity of melanoma cells to PLX4720 (BRAF inhibitor) as a result of the simultaneous activation of the MAPK and PI3K/AKT pathways." (PMID 35565444, 2022). "40% of melanoma patients possess a BRAF v600E mutation which activates the MAPK pathway resulting in excess cell proliferation and inhibited apoptosis." (PMID 35350751, 2022). "The metastatic melanomas with BRAF V600E mutation are highly responsive to BRAF inhibitors (dabrafenib and vemurafenib) initially but later display resistance a few months post-treatment." (PMID 36401282, 2022). "For example, melanomas harboring mutations of driver events in the MAPK pathway (BRAF, NRAS, NF1, KIT, and so on) have been shown to respond well to MEK/MAPK inhibitors." (PMID 35844619, 2022). "CRC patients treated with selective Ras/Raf pathway-targeted agents show limited benefits in contrast to the considerable response observed in BRAF-mutated melanoma patients." (PMID 35158939, 2022). "The present study compared RNA editing as well as gene expression in tumour cell lines from melanoma patients of short or long metastasis-free survival, patients relapsing or not after immuno- and targeted therapy and tumours harbouring BRAF or NRAS mutations." (PMID 35993275, 2022). "Melanoma patients with an activating mutation in the BRAF oncogene can be treated with BRAF inhibitors, combined with inhibitors of the downstream MAPK kinase (MAPKK or MEK)." (PMID 35409102, 2022). "Consistently, previous research has proven that BRAF mutation in melanoma patients indicates a higher overall and relative survival rate." (PMID 36532053, 2022). "About 50% of melanoma patients present mutations in BRAF gene which encodes a protein activating the mitogen-activated protein kinase (MAPK), which favors cell proliferation and survival." (PMID 36400750, 2022). "More than half of all clinical melanomas carry an activating BRAF mutation, 90% of which are BRAF V600E." (PMID 36358868, 2022). "Since most CM has activating mutations in the proto-oncogene BRAF, which is part of the Ras-Raf-MeCMk-Erk signaling pathway, this provides an essential direction for targeted therapy in melanoma targeting the MAPK pathway (BRAF and MEK inhibitors)." (PMID 36297527, 2022). "Regarding the antitumor activity of Portuguese propolis in BRAF-mutated melanoma cells, our results reveal that G18.EE and its fractions were able to reduce A375 and WM9 cell viability." (PMID 35684471, 2022). "Activating BRAF mutations are also frequently detected in some malignant carcinomas and tumors such as melanomas, promoting proliferation and drug resistance through the constitutive activation of the MAPK pathway." (PMID 36497489, 2022). "This study found that BRAF V600K mutated melanomas had a lower response rate to therapies and a greater and more rapid tendency to metastasize, with greater resistance to therapy resulting in a higher and more rapid mortality rate during follow-up." (PMID 36844955, 2022). "These, however, are limited to patients who carry the BRAF V600E/K mutations, the prevalence of which in melanoma is estimated to be ~40% to 50%." (PMID 35559986, 2022). "In light of the observation that the MST2 pathway participates in mediating cell death in PLX4032-sensitive mutant BRAF melanoma cells, we wanted to know if this pathway is associated with the acquisition of resistance to BRAFi." (PMID 36038253, 2022). "Firstly, zinc finger and BTB domain containing 11 (ZBTB11) was identified as being hyper-edited in the NRAS mutation group, when compared to melanoma samples with BRAF or other mutations." (PMID 35993275, 2022).
melanoma (continued). "Genomic analyses have shown that most nevi on low-CSD skin harbor mutually exclusively mutations in melanoma driver oncogenes, such as BRAF and NRAS." (PMID 35997352, 2022). "The development of resistance to BRAF inhibitors in a mouse melanoma model was associated with the restoration of the MDSC compartment." (PMID 35328639, 2022). "The RAS-RAF-MEK-ERK pathway is hyperactivated in most malignant melanomas, and mutations in BRAF or NRAS account for most of these cases." (PMID 36038253, 2022). "Approximately half of melanomas exhibit a mutation in the serine/threonine kinase BRAF, most often a specific change of ‘T’ to ‘A’ nucleotide at codon 600 (V600E)." (PMID 36551868, 2022). "Melanoma patients with an initial mutation in the BRAF gene (n = 24) were recruited for follow-up with ctDNA liquid biopsies (n = 91)." (PMID 36497340, 2022). "EV20/MMAF in combination with PLX4720 in BRAF mutated melanoma, and EV20/MMAF alone or plus vemurafenib resulted in an effective anti-metastatic activity in vivo." (PMID 36271429, 2022). "BRAF mutation is implicated in melanoma progression, sustained angiogenesis, tissue invasion, and metastasis, as well as the evasion of the immune response." (PMID 36614156, 2022). "The loss of MST2 pathway protein expression in BRAF inhibitor resistant melanoma cells is due to ubiquitination and subsequent proteasomal degradation and prevents MST2-mediated apoptosis." (PMID 36038253, 2022). "Among the 26 consecutive radically resected stage III–IV melanoma patients who were tested before starting adjuvant treatment, the BRAF V600E mutation was found on ctDNA only in one patient." (PMID 35804825, 2022). "As the two cases illustrate, identification of BRAF mutations not only offered our patients a systemic treatment option, but also initiated the search and identification of the primary (cutaneous) melanoma." (PMID 34142226, 2022). "In BRAF-mutated melanoma, the combination of MEKi and BRAFi has increased treatment efficacy significantly." (PMID 34837846, 2022). "Another dermoscopic trait, the blue-white veil, has been identified as a strong predictor of the presence of BRAF mutation in melanoma." (PMID 35160279, 2022). "Activation of the mitogen-activated protein kinase/extracellular signal-regulated kinase (MAPK/ERK) pathway in BRAF-mutated melanoma cells, as A375 cells, can promote hypoxia inducible factor-1 alpha (HIF1α) expression, hence leading to a high glycolytic rate." (PMID 35163570, 2022). "Accordingly, we investigated the association between PD-L1+ PMNs and clinical response in the two patient subgroups, based on the results obtained with survival, namely BRAF wild type and BRAF mutated melanoma patients." (PMID 36016960, 2022). "High genetic mutations in specific genes such as oncogenic BRAF have been discovered in patients with melanoma, hence, the importance of developing targeted therapies against BRAF signaling has increased." (PMID 36430634, 2022). "Other studies have also demonstrated the diagnostic utility of CSF ctDNA analysis, with mutation profiles generally consistent with the primary tumour type (e.g., NRAS and BRAF mutations from melanoma patients and EGFR mutations for lung BrM patients)." (PMID 35225863, 2022). "Broader accessibility to next-generation sequencing in advanced melanoma revealed further BRAF mutations in other V600 or non-V600 gene locations." (PMID 35380338, 2022). "Resistance to BRAF/MEK inhibitor therapy in BRAFV600‐mutated advanced melanoma remains a major obstacle that limits patient benefit." (PMID 34957688, 2022). "The mutations of the NF1 gene were also observed in sporadic melanomas, but it is more common in melanomas after exposure of the skin to radiation, or wild-type melanomas, which include mutations in BRAF or Nras genes." (PMID 35053664, 2022).
melanoma (continued). "Approximately 50% of melanomas are driven by an activating BRAF mutation which serves as an essential kinase in the mitogen-activated protein kinase (MAPK) pathway responsible for tumor cell proliferation." (PMID 35380338, 2022). "Vemurafenib, the first BRAF inhibitor approved for the treatment of melanoma, was associated with a 63% reduction in the risk of death compared with dacarbazine chemotherapy." (PMID 35492830, 2022). "Gain- or loss-of-function experiments in BRAF or NRAS-mutated melanoma mouse models demonstrated that ZEB1 prevents the recruitment and the activation of CD8+ T cells." (PMID 35432344, 2022). "BRAF-MEK inhibitor drugs improve survival in the approximately 50% of patients with melanoma that harbor BRAF mutations." (PMID 35756682, 2022). "HO-1 also has been shown to contribute towards dysregulated proliferation in BRAFV600E melanomas, through direct association with the BRAF protein." (PMID 35326683, 2022). "By contrast, NRAS mutations or BRAF V600K or K601E mutations are more commonly associated with intermediate melanoma lesions, which had already accumulated other pathogenic mutations." (PMID 35159386, 2022). "Vemurafenib, a BRAF inhibitor, became the first approved targeted drug for the treatment of melanoma bearing oncogenic BRAF gene mutation." (PMID 35837286, 2022). "NF-κB has been shown to interact with BRAF to increase melanoma cell survival, and NF-κB activation is reportedly caused by deregulations in the RAS/RAF, PI3K/Akt and NIK signalling pathways." (PMID 36140259, 2022). "Clinical trial in patients with advanced BRAF-mutated melanoma assessing the combination of XL888 and Vemurafenib and/or Cobimetinib are ongoing." (PMID 35326726, 2022). "In stage IV melanoma with a BRAF-V600 E/K mutation, first-line therapy with BRAF/MEK inhibitors can be proposed instead of immunotherapy." (PMID 36012593, 2022). "To investigate the potential contribution of MMDR to targeted therapy in BRAF‐mutated melanoma cells, we employed an in vitro model based on live cell‐derived 3D ECMs." (PMID 34957688, 2022). "Altogether, these studies underline the link between EVs, BRAFV600E and BRAF-inhibitor resistance in melanoma while stressing the need for additional functional and in vivo studies as well as an extension to BRAFV600E-dependent TC." (PMID 36289847, 2022). "Taken together, our data showed that PI3K–Akt activation mediated by the PIK3CA H1047R mutation promotes the proliferation and resistance of melanoma cells treated with BRAF and MEK inhibitors." (PMID 35335966, 2022). "In this study, we use CRISPR/Cas9 gene editing to introduce three point mutations associated with acquired BRAF inhibitor resistance directly into A375 human malignant melanoma cells, which carry the BRAF V600E mutation." (PMID 36358868, 2022). "To measure the kinase activity of CDK12, we performed in vitro kinase reactions using endogenous CDK12 immunoprecipitated from A375, a BRAF-mutated melanoma cell line." (PMID 36309522, 2022). "We studied a total of 24 advanced melanoma patients with an initial tissue mutation in the BRAF gene, and we performed a total of 92 ctDNA liquid biopsies during follow-up." (PMID 36497340, 2022). "The V600E mutated BRAF kinase acts as driver oncogene in many cancers, particularly melanoma and colorectal cancer, and can be therapeutically targeted using small kinase inhibitors." (PMID 36139087, 2022). "For example, BRAF, although is, indeed present (the mutated form) in 50% of melanomas, this BRAF mutation is also expressed in benign pigmented lesions." (PMID 35574390, 2022). "Here, we present 3-year follow-up data for patients in the KEYNOTE-151 study, including subgroup analyses by melanoma subtype and by PD-L1 and BRAF mutation status in patients with acral melanoma." (PMID 36304457, 2022).
melanoma (continued). "Considering the initial evidence on the efficacy of dabrafenib plus trametinib in BRAF K601E-mutated melanoma and lung cancers, it would be interesting to evaluate this combination in mCRPC patients harboring this specific mutation in the future." (PMID 35955671, 2022). "Similar results were obtained in PDX models of BRAF-V600E-mutant melanoma refractory to BRAFi/MEKi therapy which harbored mutations in NRAS and CDKN2A." (PMID 35565444, 2022). "BRAF mutation is known to negatively influence the overall prognosis in several tumor indications, for example, malignant melanoma, papillary thyroid cancer, and so on." (PMID 35130969, 2022). "In melanoma, mutations in BRAF are found in approximately 40% of cases and result in constitutive activation of the MAPK pathway." (PMID 36212431, 2022). "In adults, BRAF-mutated tumors include 60% of melanomas, 60% of thyroid cancers, 15% of colorectal cancers, and 5% to 8% of non–small cell lung cancers, with the most prevalent mutation being BRAFV600E." (PMID 34737188, 2022). "HMGB1 was released passively in the extracellular space by dying cells both in wild-type and BRAF mutated melanoma cells." (PMID 36012593, 2022). "As CCT196969 has been suggested as a potential second line treatment for BRAF inhibitor resistant melanoma and first line therapy for NRAS- and BRAF-mutated melanoma, combination therapy with PI3K inhibitors should be investigated in the future." (PMID 36084109, 2022). "Dabrafenib is another BRAF inhibitor approved by the FDA in 2013 with a long history of use as both a solo first-line therapy in BRAF V600E-mutated late-stage melanoma as well as in combination regimens." (PMID 35954441, 2022). "Elevated phosphorylated MEK and ERK concentration was revealed for BRAF L597Q/R/S expression, and in vitro and in vivo tumor regression was shown for L597S- and L597Q-mutated melanoma when treated with a MEKi." (PMID 35380338, 2022). "Second line anti-PD1 immunotherapy is effective in selected BRAF-mutated melanoma patients after BRAFi/MEKi immunotherapy failure." (PMID 35565255, 2022). "The prognosis of patients with BRAF-mutated melanoma has greatly improved in the last 10 years thanks to the advent of these new drugs." (PMID 36046043, 2022). "This trial provided the first prospective evidence of the optimal sequence of immune checkpoint inhibitor therapy and targeted treatment combination choice in patients with BRAF-mutated advanced melanoma." (PMID 35456332, 2022). "The divergence in survival rates reveals a critical problem: the existing inadequacies in care for individuals with BRAF-mutated melanoma." (PMID 36589179, 2022). "Recently, it has also been reported that the knockout of ATF4 can reduce the resistance of gastric cancer cells to cisplatin or increase the sensitivity of BRAF-mutated melanoma to vemurafenib." (PMID 35864117, 2022). "Recent studies have found that lncRNAs are associated with BRAF mutation and the growth of melanoma cells." (PMID 36601121, 2022). "For example, in patients with Her2-positive breast cancer BMs, those with ALK-rearranged or EGFR-mutated NSCLC BMs, and for BRAF V600 E mutated melanoma BMs, targeted therapies with significant intracranial activity are available." (PMID 36605448, 2022). "BRAF mutation occurs at an early stage of melanoma and drives the melanocyte malignant transformation." (PMID 36551302, 2022). "Assessment of BRAF mutation status is mandatory in advanced, previously untreated melanoma patients since it is present in 40–50% of cases and allows treatment with specific inhibitors." (PMID 35159044, 2022). "The VE-BASKET trial (an open-label non-randomized trial assessing the BRAF inhibitor vemurafenib in BRAF V600-mutated non-melanoma cancers) reported an objective response rate of 25% across all gliomas studied." (PMID 36619621, 2022).